OPN4 (opsin 4)
Diseases named in the same sentence as OPN4 in open-access papers:
OPN4 is named in the same sentence as 46 diseases in open-access papers, as found by Europe PMC text mining. Sharing a sentence is not in itself a finding about the gene and the disease. The quoted sentences say what the papers report.
melanoma (7 papers, 2017 to 2022). A malignant, usually aggressive tumor composed of atypical, neoplastic melanocytes. "Additionally, it has also been found that the expression of OPN4 decreases in human melanoma, and its downregulation is significantly associated with tumor metastasis and poor prognosis." (PMID 35805166, 2022). "Our findings are suggestive that OPN4 acts as an oncogene, but additional experiments using human melanoma cell lines and different approaches, i.e., knockdown, knockout, and/or rescue strategies are required to fully establish the OPN4 role as an oncogene." (PMID 35562405, 2022). "Our data show that high expression of OPNa, OPNb, and especially OPNc and low expression of OPN4 and ITGA2 are associated with an advanced stage of tumor progression and poor prognosis in melanoma." (PMID 36091936, 2022). "In human melanoma, OPN4 expression decreases with disease progression, and tumors expressing low levels of OPN4 also display increased levels of BMAL125." (PMID 35562405, 2022). "Taken altogether, our data add a novel layer of complexity to the opsin realm as we provide evidence that OPN4 can be a tumor oncogene in melanoma." (PMID 35562405, 2022). "Taken together, the expression of OPN4 and OPN5 splice variants appears to vary widely in distinct tumor types, but in melanoma, they slightly have a different expression profile than the three predominant splice variants." (PMID 36091936, 2022). "We provided evidence that a light- and thermo-sensing protein, OPN4, whose role as an important light sensor responsible for circadian entrainment has been well established, plays a pro-tumoral role in melanoma." (PMID 35562405, 2022). "Evaluation of Tumor Cancer Genome Atlas (TCGA) database confirms our experimental data as reduced MITF and OPN4 expression in human melanoma correlates with slower cell cycle progression and presence of immune cells in the tumor microenvironment (TME)." (PMID 35562405, 2022). "All these findings further provided robust evidence of an intriguing role of OPN4 in a light- and thermo-independent fashion that can be appreciated as an oncogene in melanoma." (PMID 35562405, 2022). "Our data show that high expression of OPNa, OPNb, and OPNc is associated with poor prognosis, and OPN4 and ITGA2 may have an opposite role in melanoma progression." (PMID 36091936, 2022). "Taken altogether, we provide evidence that OPN4 can act as an oncogene in melanoma." (PMID 35562405, 2022). "In this study, we evaluated the putative role of OPN4 in the carcinogenic process of melanoma." (PMID 35562405, 2022). "Therefore, we suggest that OPN4 can be seen as a tumor oncogene in melanoma and could be pharmacologically targeted." (PMID 35562405, 2022). "Such evidence points to OPN4 as an oncogene in melanoma, which could be pharmacologically targeted." (PMID 35562405, 2022). "Therefore, in this study, our primary aim was to study the expression profile of five OPN splice variants (OPNa, OPNb, OPNc, OPN4, and OPN5) in different types of malignant melanoma tissues and investigate the association with the clinicopathological features of tumor tissues." (PMID 36091936, 2022). "Such modifications may place Opn4 as a putative tumor suppressor gene in melanoma." (PMID 34698095, 2021). "When melanocyte cells were irradiated with UVA, the expression of OPN2, OPN4, CLOCK, BMAL1, PER1, and XPA was increased in murine Melan-A melanocytes and B16-F10 melanoma." (PMID 35270025, 2022). "The expression of the recently described OPN4 and OPN5 isoforms was shown to be downregulated in the evaluated melanoma subtypes, and OPN4 exhibited a significant negative correlation with Breslow thickness." (PMID 36091936, 2022). "Subsequently, bioinformatic analysis found a negative correlation between OPN4 expression and the progression of human melanoma." (PMID 35270025, 2022).
melanoma (continued). "Using different experimental approaches, we show that melanoma cell proliferation is slower in the absence of Opn4, compared to Opn4WT due to an impaired cell cycle progression and reduced melanocyte inducing transcription factor (Mitf) expression." (PMID 35562405, 2022). "To this end, we investigated how the absence of OPN4 in tumor cells would affect the development and progression of melanoma in a murine model." (PMID 35562405, 2022). "Subsequently, the same team further explored the unique function of Opn4 on responses to UVA radiation, including regulation of proliferation, apoptosis, pigmentation, and molecular clock, and found that UVA-induced effects are abrogated in murine normal melanocytes and Opn4 absence melanoma cells." (PMID 35805166, 2022). "Conversely, a negative correlation between OPN4 levels and the abundance of several immune cells, such as B and CD4+ lymphocytes, and M1 macrophages was found; a positive correlation was found for mast cells and neutrophils in human melanoma." (PMID 35562405, 2022).
myopia (5 papers, 2021 to 2026). "OPN4 knock-out mice exhibit greater hyperopia compared to wildtype mice; however, they are also more susceptible to form-deprivation myopia (FDM)." (PMID 39720655, 2024). "The loss of melanopsin resulted in shorter ALs and hyperopic refractions in both models, although Opn4−/− mice had a steeper refractive development curve with more myopia at young ages and more hyperopia at older ages compared to WT mice." (PMID 38635876, 2024). "Supporting the notions that OPN4 may participate in the underlying mechanisms mediating emmetropization or ametropias, the mRNA levels for OPN4 oscillate during the day, and these oscillations are perturbed in both retina and choroid of chick eyes developing myopia or hyperopia." (PMID 39151779, 2024). "Recently, non-visual opsins (OPN3, OPN4, and OPN5) have emerged as potentially impacting myopia regulation." (PMID 41620773, 2026).
Alzheimer disease (3 papers, 2021 to 2025). A progressive, neurodegenerative disease characterized by loss of function and death of nerve cells in several areas of the brain leading to loss of cognitive function such as memory and language. "Regarding the therapeutic perspective, the functions and associations of OPN4, along with the alterations caused by its SNPs, are valuable due to their connections to health issues such as Alzheimer’s disease, Parkinson’s disease and autism spectrum disorder." (PMID 40556870, 2025).
cutaneous melanoma (3 papers, 2022 to 2025). A primary melanoma arising from atypical melanocytes in the skin. "OPN4 is a gene closely related to visual perception and circadian rhythm, serving as a light sensor in the circadian rhythm, and it is also an oncogene in cutaneous melanoma." (PMID 39981438, 2025). "OPN-4 is a marker for stage in renal clear cell carcinoma, kidney chromophobe, uterine carcinosarcoma, hepatocellular carcinoma, and – in conjunction with OPN-a and OPN-b – in cutaneous melanoma." (PMID 37095438, 2023).
breast carcinoma (2 papers, 2022 to 2025). "The results indicated that high expression levels of OPN4, NOS2, GPR157, NCOA2, CLOCK, and TH were associated with shorter OS in breast cancer patients, while high expression of EGR3, NR1H3, RELB, SIAH2, and ADRB1 was linked to improved survival rates." (PMID 41031266, 2025). "Except for in the two breast cancer cell lines, OPN4 and OPN5 were found to be co-expressed in the other 5 cell lines, but the expression patterns differed from those of the previously characterized OPNa, OPNb, and OPNc variants." (PMID 36091936, 2022).
esophageal adenocarcinoma (2 papers, 2022). A malignant tumor with glandular differentiation arising predominantly from Barrett mucosa in the lower third of the esophagus. "OPNa, OPNb, and OPNc variants were first described in glioma, and the two additional splice variants (OPN4 and OPN5) were found in esophageal adenocarcinomas and glioblastomas." (PMID 36091936, 2022). "In 2015, the expression of OPN4 and OPN5 were detected in esophageal adenocarcinoma by Lin etal." (PMID 36064446, 2022).
hepatocellular carcinoma (2 papers, 2021 to 2023). A malignant tumor that arises from hepatocytes. "The impact of OPN3 or OPN4 on tumor cell activities, such as drug sensitivity, growth, and metastasis, has been reported in hepatocellular carcinoma, colon cancer, and lung adenocarcinoma, and blue light (465 nm) exposure suppresses tumor growth by inducing autophagy." (PMID 34682694, 2021).
insomnia (2 papers, 2021 to 2025). A sleep disorder characterized by difficulty in falling asleep and/or remaining asleep. "This information, along with the previous association of the polymorphism and the functions of OPN4, indicates a connection with the OPN4 gene, its SNPs, and insomnia." (PMID 40556870, 2025). "We analyzed—by genotyping—a group of insomnia patients to look for an association of the P10L polymorphism OPN4 gene." (PMID 33445464, 2021). "We performed the genotyping of control and insomnia subjects seeking for the occurrence of OPN4 alleles variants." (PMID 33445464, 2021). "There is a strong association between the occurrence of the OPN4 gene P10L SNP and insomnia, genotype distributions in the control group were in agreement with the Hardy–Weinberg equilibrium." (PMID 33445464, 2021). "Hence, we wanted to seek an association between the P10L polymorphism OPN4 gene and insomnia." (PMID 33445464, 2021).
sleep disorder (2 papers, 2016 to 2025). A change from the patient's baseline sleeping pattern, in the hours slept and/or an alteration/dysfunction in the stages of sleep. "Variations in the OPN4 gene, such as P10L and I394T SNPs, may impact individuals’ sensitivity to light by altering the response properties of ipRGCs and making them more susceptible to mood disorders, sleep disturbances, or metabolic diseases." (PMID 40556870, 2025).
atherosclerosis (1 paper, 2025). A disease characterized by the build-up of fatty material and calcium deposition in the arterial wall resulting in partial or complete occlusion of the arterial lumen. "Interestingly, the observed pattern of certain mutations, such as the OPN4 mutation, which spanned the media and subcore intima samples, is similar to that of SMC growth/migration, and aligns with the known capacity SMCs to proliferate and form clones in experimental atherosclerosis." (PMID 40198128, 2025).
Blindness (1 paper, 2022). Blindness is the condition of lacking visual perception defined as a profound reduction in visual perception. "The double mutant animal model Opn4−/− × Rd10, obtained from crosses between carriers of a mutation in the Pde6b gene and in the Opn4−/− gene, has been thoroughly characterized as a model of absolute blindness." (PMID 35897728, 2022). "In this work, an animal model of absolute blindness has been exhaustively characterized, generated by crossing mice with photoreceptor degeneration (Rd10) and mice that present a mutation that inhibits the synthesis of melanopsin (Opn4−/−)." (PMID 35897728, 2022). "The objective is to verify that the Opn4−/− × Rd10 (O×Rd) model meets the necessary requirements to consider its blindness as absolute." (PMID 35897728, 2022).
COVID-19 (1 paper, 2021). A disease caused by infection with severe acute respiratory syndrome coronavirus 2. "The expression of OPN3 and OPN4 in airway smooth muscle also suggested the impact of blue light exposure on vasorelaxation for the treatment of pulmonary disorders caused by COVID-19." (PMID 34682694, 2021).
epilepsy (1 paper, 2021). A brain disorder characterized by episodes of abnormally increased neuronal discharge resulting in transient episodes of sensory or motor neurological dysfunction, or psychic dysfunction. "Patient II, a girl (14 years of age) diagnosed with ID and affected by epilepsy, carried a frameshift de novo variant c.5573_5576 (p.(Lys1859Asnfs * 2)) of PCDH15 and a de novo splicing variant c.1074–11G > A of OPN4." (PMID 34948243, 2021).
glaucoma (1 paper, 2016). Increased pressure in the eyeball due to obstruction of the outflow of aqueous humor. "However, the TT risk allele of the OPN4 SNP P10L that has been associated with sleep disturbances was present in only one participant (an early glaucoma patient)." (PMID 27622679, 2016). "Notably, the I394T genotype did not affect any of the pupil metrics, suggesting that this OPN4 gene variant was not a contributor to the lower PIPR and PLR responses in the glaucoma patients." (PMID 27622679, 2016).
influenza (1 paper, 2023). An acute viral infection of the respiratory tract, occurring in isolated cases, in epidemics, or in pandemics; it is caused by serologically different strains of viruses (influenzaviruses) designated A, B, and C, has a 3-day incubation period, and usually lasts for 3 to 10 days. "As we identified an association between tOPN and OPN4 detection and influenza A(H1N1)pdm09 infection, we further investigated the relationship between their prevalence in the cases that also presented severe influenza symptoms such as dyspnea, respiratory failure, and oxygen saturation." (PMID 37317323, 2023).
metastatic tumors (1 paper, 2022). "Gene expression analyses revealed that the relative expression of OPNa, OPNb, and OPNc is significantly higher in metastatic tumors compared to primary lesions (p < 0.01), whereas the expression of OPN4 and OPN5 was low in both." (PMID 36091936, 2022).
Mydriasis (1 paper, 2021). Abnormal dilatation of the iris. "We also found some marine mammal species to lack several phosphorylation sites in the carboxyl terminal domain of their Opn4 pigments that result in significantly slower deactivation kinetics, and thus longer mydriasis, compared to terrestrial controls." (PMID 34653198, 2021). "In mammals, the photopigment melanopsin (Opn4) is found in a subset of retinal ganglion cells that serve light detection for circadian photoentrainment and pupil constriction (i.e., mydriasis)." (PMID 34653198, 2021).
Neurodegeneration (1 paper, 2023). Progressive loss of neural cells and tissue. "The visual functions of the animal model of retinal neurodegeneration induced by the administration of sodium iodate (NaIO3) combined with a knockout mutation of the Opn4 gene (Opn4−/−) have been extensively characterized." (PMID 37627589, 2023).
night blindness (1 paper, 2019). Inability to see clearly in dim light. "LFPs were also nearly absent in a model of stationary night blindness, in which the photoreceptor cells are morphologically intact, but lack light-sensing function (Gnat1−/−, Gnat2−/−, Opn4−/−) 22–24." (PMID 31537864, 2019).
respiratory failure (1 paper, 2023). The significant impairment of gas exchange within the lungs resulting in hypoxia, hypercarbia, or both, to the extent that organ tissue perfusion is severely compromised. "OPN4 detection was also associated with severity symptoms such as dyspnea (p < 0.05), respiratory failure (p < 0.05), and oxygen saturation < 95% (p < 0.05)." (PMID 37317323, 2023).
retinal degeneration (1 paper, 2022). Degeneration of the retina. "It was observed that the animal models of retinal degeneration (Rd10 and Opn4−/− × Rd10) showed serious damage to the outer layers of the retina (outer segments of the photoreceptors and outer nuclear layer), as they lacked labeling compared to non-degenerate models (C57BL/6J and y Opn4−/−)." (PMID 35897728, 2022). "The differences between the animals that do not suffer degenerative processes (C57 and Opn4−/−) and the models with retinal degeneration (Rd10 and O×Rd) are extremely significant (two-way ANOVA, p < 0.0001)." (PMID 35897728, 2022).
cancer (6 papers, 2018 to 2023). A tumor composed of atypical neoplastic, often pleomorphic cells that invade other tissues. "Collectively, loss of OPN4 may result in a more resistant phenotype against the deleterious effects of UV radiation and faster proliferation (these data), leading to an increased likelihood of mutation accumulation and cancer development." (PMID 34698095, 2021). "In human cancer cell lines, results indicated that OPN4 and OPN5 transcripts displayed co-expressed in most have been assessed cell lines except for MDA-MB-231 and MCF-7, which only express OPN5." (PMID 36064446, 2022). "In a recent work on human OPN-SV the expression profile of osteopontin-4 (OPN4) and osteopontin-5 (OPN5) has been addressed in distinct cancer cell lines." (PMID 36064446, 2022). "Whereas there are nine rhythm genes (MTNR1B, NR1D1, RORB, RORA, OPN4, C1orf51, PROK2, SERPINE, and EGR3) that are differently expressed in the high and low MSI group in more than 1/3 cancer types." (PMID 31927791, 2020). "We also recently found that OPN-4 and OPN-5 are co-expressed in several human cancer cell lines and tumor tissues, further evidencing their roles in cancer biology, as has been previously found in several reports regarding OPN-a, OPN-b, and OPN-c splice variants." (PMID 36769264, 2023). "Expression of all the 23 target genes changed in HT1080 cells; 20 genes were up-regulated and two genes PDGFR β and WRNIP1 were down-regulated (OPN4 did not change significantly; PDGFR β decrease on TRF2 silencing in cancer cells was also noted earlier)." (PMID 30439955, 2018).
tumor (6 papers, 2021 to 2026). "In our study, decreased MITF and OPN4 (also higher BMAL1) gene expression is associated with a slower proliferation, higher antitumorigenic TME, and therefore, reduced tumor growth." (PMID 35562405, 2022). "We have previously shown that OPN4 expression decreases as tumor aggressiveness increases in humans." (PMID 35562405, 2022). "Therefore, different layers of evidence suggest impaired guanylyl cyclase activity in the absence of OPN4, which we suggest being one of the mechanisms by which removal of OPN4 reduces tumor growth and proliferation." (PMID 35562405, 2022). "To evaluate whether OPN4 would impact tumor development, we inoculated C57Bl/6 J mice, kept in thermoneutrality (30 ± 1 °C), with B16-F10 Opn4WT or B16-F10 Opn4KO cells." (PMID 35562405, 2022). "Taken altogether, we demonstrated that OPN4 regulates cell proliferation, cell cycle, and affects the expression of several important factors of the melanocyte physiology; thus, arguing for a putative tumor suppression role in melanocytes." (PMID 34698095, 2021). "Moreover, by estimating the frequency of immune cells in the tumor bulk, we found an interesting correlation between MITF and OPN4 with different immune cell types that is suggestive of a role of OPN4 in TME and consequently tumor progression." (PMID 35562405, 2022). "Excluding genes not detected (OPN4, PIGF), gene NONO was more highly expressed in BRCA tumor tissue (BRCA tissue) than in normal breast tissue (Normal breast tissue)." (PMID 40826746, 2025). "An IHC analysis was implemented on gene expressions in BRCA tumor tissue and normal breast tissue, with HR values >1 (NONO, OPN4, PIGF) in the Cox model by using the Human Protein Atlas database." (PMID 40826746, 2025).
OPN4 also shares sentences with these, for which no sentence is quoted: hyperopia (2 papers); Anxiety (1); autism spectrum disorder (1); bipolar disorder (1); colon cancer (1); dementia (1); depression (1); dilated cardiomyopathy (1); glioblastoma (1); glioma (1); hypertrophic cardiomyopathy (1); kidney chromophobe (1); lung adenocarcinoma (1); metabolic disease (1); metastatic melanoma (1); mood disorder (1); nodular melanomas (1); Parkinson disease (1); pulmonary disorders (1); renal clear cell carcinoma (1); schizophrenia (1); Sleep disturbance (1); uterine carcinosarcoma (1).